PRR20A (proline rich 20A)
Synonyms: PRR20; FLJ40296
Tractability: No criterion of Open Targets' tractability assessment is met for any kind of drug.
Gene: Protein-coding gene on chromosome 13 (57,140,918 to 57,143,939, forward strand). Ensembl gene ENSG00000204919.
Homologues: Orthologues: dog PRR20G (38% identical). Paralogues in human: PRR20B (100% identical), PRR20C (100% identical), PRR20D (100% identical), PRR20E (100% identical), PRR20G (53% identical).
Diseases named in the same sentence as PRR20A in open-access papers:
PRR20A is named in the same sentence as 1 disease in open-access papers, as found by Europe PMC text mining. Sharing a sentence is not in itself a finding about the gene and the disease.
PRR20A shares sentences with these, for which no sentence is quoted: cancer (1 paper).